FLJ16779 (uncharacterized LOC100192386 )
Gene: Long non-coding RNA gene on chromosome 20 (63,253,978 to 63,261,615, forward strand). Ensembl gene ENSG00000275620.
Diseases named in the same sentence as FLJ16779 in open-access papers:
FLJ16779 is named in the same sentence as 1 disease in open-access papers, as found by Europe PMC text mining. Sharing a sentence is not in itself a finding about the gene and the disease. The quoted sentences say what the papers report.
cancer (1 paper, 2023). A tumor composed of atypical neoplastic, often pleomorphic cells that invade other tissues. "We also found a few novel lncRNAs such as LINC00940 and FLJ16779 that have not been reported earlier besides SNHG19, NPBWR1, and lncRNAs that are known to be involved in cancer and other diseases as well." (PMID 37218885, 2023).